HIF1A (hypoxia inducible factor 1 subunit alpha)
Diseases named in the same sentence as HIF1A in open-access papers (continued):
Sharing a sentence is not in itself a finding about the gene and the disease.
ischemia (continued). "Given the significance of the VHL-HIF-1α interaction in determining HIF-1α abundance, efforts have been made to develop small-molecule drugs targeting this interaction for the treatment of conditions like chronic anemia and ischemia." (PMID 40691138, 2025). "The end product lactate stabilizes HIF-1α, activates the VEGF signaling pathway and VEGFR2 expression, promotes angiogenesis, and aids in revascularization and damaged tissue regeneration post-ischemia." (PMID 41471391, 2025). "In diabetic contexts, where Akt/HIF-1α/VEGF signaling is typically impaired, Ethacridine-induced restoration of this pathway may alleviate local ischemia and promote neovascularization, thereby accelerating tissue regeneration." (PMID 41150817, 2025). "It is worth mentioning that activation of HIF-1α during AIS may help to attenuate nerve tissue damage and dysfunction induced by ischemia, but this depends on the different types of nerve cells." (PMID 39926015, 2025). "Relating these findings to the HIF1α immunoreactivity, this indicates that the first occurrence of histomorphological mucosal damage at ischemia does not necessarily correlate with an increase in enterocyte HIF1α immunoreactivity seen at reperfusion." (PMID 36908508, 2023). "When oxygen delivery is compromised as is the case with respiratory distress syndrome and ischemia in COVID-19, HIF-1α escapes degradation, allowing it to migrate to the nucleus and induce transcription of HIF-1α target genes, including those involved in glycolysis and erythropoiesis." (PMID 35680931, 2022). "The neuroprotection induced by LEV may involve a variety of mechanisms, including suppression of the inflammatory response induced by ischemia, increasing the expression of VEGF, HIF-1α, and HSP70, and reducing neuronal apoptosis." (PMID 34054520, 2021). "Hif1α and Vegfa expression were depressed in the first and second-months post-ischemia, and then Hif1α but not Vegfa expression was recovered." (PMID 33888767, 2021). "Subjecting the ischemia-affected CMC to secretome, time-dependent increase of HIF-1α and RhoA expression could be detected, indicating that cell-free therapy might be considered as a more viable option for cardiac regeneration." (PMID 33123511, 2020). "Chlorogenic acid (and its metabolite dihydrocaffeic acid) administered either before or after ischemia reduced brain infarct volume, BBB damage and behavioral deficits in tMCAO rats by blunting MMP activation and increasing brain levels of EPO, HIF-1a and nerve growth factor (NGF)." (PMID 33383852, 2020). "We show that STAT3 regulates angiogenic and metabolic pathways before HIF1α, suggesting that HIF1α is not the initiating trans-acting factor in the response of pericytes to ischemia." (PMID 29518129, 2018). "Many studies have demonstrated that HIF-1α is activated in AKI with or without ischemia and ameliorates AKI by improving hypoxia." (PMID 30127742, 2018). "Hypoxic preconditioning elicits HIF-1α-dependent upregulation of genes, including VEGF-A, not only during the preconditioning period, but also at an elevated rate during a subsequent ischemia, suggesting that the treatment modifies the brain’s genomic response to ischemia." (PMID 29734653, 2018). "Moreover, accumulation of HIF-1α and HIF-2α by pharmacological inhibition of prolilhydroxylases (PHDs) administration to mice results in renal protection against ischemia." (PMID 28106131, 2017). "The absence of the HIF-1α dependent genes would enhance the maladaptive renal regeneration after ischemia allowing a chronic renal damage as a long-term outcome of renal I/R episode." (PMID 28106131, 2017). "However, the sciatic nerves of the diabetic rats suffered ischemia and hypoxia, and VEGF was adaptively upregulated in a manner that depended on activated HIF-1α." (PMID 27057201, 2016).
ischemia (continued). "HIF-1α stability in interneurons was consistent with an increase in intracellular GSH levels, suggesting that interneurons contain a highly reducing environment that maintains HIF-1 stability and expression during ischemia." (PMID 24887017, 2014). "It is demonstrated that hypoxia-inducible factor-1α (HIF-1α), interleukin-1 β (IL-1β) and tumor necrosis factor α (TNF-α) expression increase in the rat brain during cerebral ischemia induced by different models of ischemia." (PMID 23351182, 2012). "These ischemia-induced alterations include increased retinal cell death (i.e., ARPE-19), a reduction in ERG b-wave amplitude, decreased fluorogold-labeled RGC density, and upregulation of neovascular/angiogenic/inflammatory, including β-catenin, HIF-1α, VEGF, and Ang-2." (PMID 41303406, 2025). "Indeed, when implanted into ischemic hindlimb, we found that HIF-1α+/+ hMSCs but not HIF-1α−/− hMSCs induced a superior recovery of blood perfusion in the hindlimb ischemia mouse model." (PMID 37158785, 2024). "Accumulation of HIF‐1α at the lesion site of CNS has been shown to promote neuronal cell death and activate inflammation, and suppression of HIF‐1α remarkably decreases the transition of reactive astrocytes and inflammatory activation in a rodent ischemia model." (PMID 37334735, 2023). "However, the involvement of HIF-1α in the amorfrutin B-evoked decrease in PPARγ expression during ischemia cannot be excluded as amorfrutin B does not affect this factor during ischemia." (PMID 34440058, 2021). "Furthermore, the expressions of HIF-1a, VEGF, PDGF, VCAM-1, and ICAM-1 mRNA were all significantly increased in WIRS control group, signifying that pathogenesis of WIRS was related to ischemia and defective blood supply." (PMID 32801474, 2020). "However, despite this considerable circumstantial evidence, previous studies have not yet explored the effect of HIF-1α on BDNF/TrkB/CREB pathway in improving synaptic plasticity following ischemia/reperfusion injury." (PMID 32670026, 2020). "However, it is not clear about the interaction of HIF-1α with MMP-2 in BBB damage during acute ischemia." (PMID 30233326, 2018). "Lactate and pyruvate accumulation stabilizes HIF-1α in the absence of ischemia." (PMID 29045486, 2017). "Hif1α−/− mice are embryonically lethal whereas Hif1α heterozygotes (Hif1α+/−), although viable, are defective in expressing the angiogenic factor vascular endothelial growth factor (VEGF) and fail to induce adaptive arteriogenesis in the mouse hindlimb ischemia model." (PMID 28781077, 2017). "Previous data from our laboratory demonstrate that HIF-1α stability requires a reducing environment during ischemia and that increases in glutathione (GSH) levels stabilize HIF-1α in cortical neurons, indicating that protein levels of HIF-1α may vary among cells with different redox statuses." (PMID 24887017, 2014). "Taking into account that HIF-1α levels were increased at the 3 postoperative time points in the group with adverse cardiac events, it is possible that new ischemia may be occurring in CHD patients undergoing non-cardiac surgery due to surgical stress and trauma." (PMID 23526997, 2013). "In a femoral artery ligation model with HIF-1α gene knockout, it was found that vascular growth factors such as VEGF were not activated, and the ability of reperfusion after ischemia was reduced." (PMID 35684364, 2022). "An explanation for the absent relationship between chromosome 8q status and ischemia in our study may be that gain of 8q is an early event (occurring in smaller, non-hypoxic cases of UM) and that 8q gain is not directly related to other strong activators of HIF1a." (PMID 31323773, 2019). "Since HIF-1α and VEGF-A expression was not increased in the retina including retinal blood vessels, endothelial dysfunction and impaired autoregulation do not appear to induce ischemia in retinal tissue." (PMID 31976030, 2019).
ischemia (continued). "RPE-derived HIF-1α plays a key role in CNV, but not in ischaemia-induced retinal NV." (PMID 24533641, 2014). "Likewise, cerebral ischemia in normal littermate (NL) mice, but not in HIF-1α-knockout (HIF-1α KO) mice, induced substantial STI-1 expression 24 h post-ischemia." (PMID 23836498, 2013). "It is noteworthy that HIF-1α and HIF-2α protein expression was downregulated not just at 24 h after reperfusion, presumably driven in part by increased tissue oxygen availability, but also 5 days after reperfusion, when tissue Po2 was similar in rats exposed to ischemia and sham ischemia." (PMID 30110566, 2018). "In addition, HIF-1α+/+ hMSCs also attenuated the ischemia-induced inflammation characterized by massive infiltration of CD45-positive immune cells and elevated release of inflammatory cytokine TNF-α, which was not the case upon transplantation of HIF-1α−/− hMSCs." (PMID 37158785, 2024).
Obesity (195 papers, 2010 to 2026). Accumulation of substantial excess body fat. "Several key signaling pathways, such as PI3K/AKT/mTOR, NOTCH, and HIF-1α signaling pathways, are involved in obesity-associated cancer development and progression." (PMID 40863244, 2025). "The synergistic constituents of Coptidis Rhizoma-Scutellariae Radix, namely BBR and WOG, synergistically alleviate IR associated with obesity by inhibiting HIF-1α and activating HIF-2α, respectively." (PMID 41039626, 2025). "Hif1a is a master regulator of hypoxia responses and has been implicated in obesity and metabolic dysfunction." (PMID 41463345, 2025). "Elevated PA in individuals with obesity can cause LOX dysregulation via activation of HIF-1α, resulting in abnormal collagen deposition in the ovary and anovulation." (PMID 38333108, 2024). "Increased PA in individuals with obesity can cause LOX upregulation via the activation of hypoxia-inducible factor-1α (HIF-1α), resulting in abnormal collagen deposition in the ovary and anovulation, which can be ameliorated by metformin therapy." (PMID 38333108, 2024). "Here, we employed a doxycycline-inducible adipocyte Hif1a knockout system to evaluate the muscle-protective effects associated with HIF1α inactivation-induced healthy AT remodeling in a model of sarcopenic obesity." (PMID 36875847, 2023). "HIF-1α is a key promoter of obesity-associated cancer due to its effect on multiple pathways that contribute to tumorigenesis." (PMID 37233716, 2023). "Obesity causes rapid adipose tissue expansion, leading to the activation of hypoxia-inducible factor 1-alpha (HIF1-α)." (PMID 38259298, 2023). "Literature-derived evidence indicates that the major clinical triggering factors of HS, obesity, and smoking are associated with hypoxia and enhanced HIF-1α expression." (PMID 36961533, 2023). "(iv) Experimental and translational studies suggest that either genetic manipulation or pharmacological inhibition of HIF1α and HIF2α in both adipose tissue and small intestine can ameliorate obesity-associated metabolic diseases (, and references therein)." (PMID 34359934, 2021). "Adipose HIF-1α causes obesity and associated metabolic dysfunction by suppressing brown adipose tissue thermogenesis." (PMID 34889901, 2021). "Hepatocyte-specific HIF-1α deficiency also protects the mice from obesity and steatosis and liver necrosis caused by hepatotoxic substances." (PMID 33816466, 2021). "The HIF1α pathway has itself been validated to play a role in metabolic diseases, where HIF1α deficient mice are protected against diet-induced obesity and insulin resistance." (PMID 32785109, 2020). "In obesity-related heart failure with preserved ejection fraction (HFpEF), HIF-1α is responsible for recruiting M1 macrophages that mediate obesity-associated inflammation." (PMID 32655760, 2020). "Genetic deletion of HIF1α in adipocytes decreases the risk of obesity-induced inflammation and insulin resistance." (PMID 33633579, 2020). "TNF-α is one of the most extensively studied pro-inflammatory cytokines, which shows a prominent link to the onset of metabolic disorders via inducing the obesity-associated HIF-1α and low-grade chronic inflammation of the adipose tissue." (PMID 32752112, 2020). "We observed that GrB expression in VAT was associated with HIF1a, a main marker of hypoxia, which is linked to the expansion of AT in obesity." (PMID 33312176, 2020). "Here we defined the metabolic programs engaged in adipose tissue macrophages in the context of obesity, and demonstrated that this is directly linked to their proinflammatory phenotype via the transcription factor HIF-1α." (PMID 32221369, 2020). "Hypothalamic inhibition of HIF-1α aggravates obesity-associated metabolic phenotype; this highlights the hypothalamic HIF-1α as a potential target for therapeutic intervention against obesity." (PMID 30443205, 2018). "Hif1a is associated with dietary obesity by restricting fatty acid oxidation through repression of SIRT2." (PMID 28445509, 2017).
Obesity (continued). "Obesity is associated with local tissue hypoxia and elevated hypoxia-inducible factor 1 alpha (HIF-1α) in metabolic tissues." (PMID 27094951, 2016). "Previous studies have functionally implicated HIF1α (6, 12, –, 14) and different PHDs in the process of obesity." (PMID 26572826, 2016). "First, in the present study we analyzed the association between VAT HIF-1α and several obesity-related variables and the mRNA expression of genes involved in lipogenesis." (PMID 26619907, 2015). "During the early stages of obesity, hypoxic conditions cause an increase in the level of Hif-1α expression in mice on a HFD and in genetically obese ob/ob mice." (PMID 22389718, 2012). "In early stage of obesity, the elevated expression of HIF-1α is associated with fibrosis and insulin resistance in white adipose tissue." (PMID 23050013, 2012). "Obesity is associated with tissue hypoxia and the up-regulation of hypoxia inducible factor 1 alpha (HIF-1α)." (PMID 23049707, 2012). "Prior studies in transgenic mice have shown that HIF-1α plays a role in the metabolic dysfunction associated with obesity." (PMID 23049707, 2012). "Therefore, targeting HIF-1α and the associated pro-inflammatory macrophage response represent a potential therapeutic approach to limit the detrimental effect of obesity on the heart." (PMID 39198360, 2025). "Additionally, ferroptosis signaling has been proposed to limit HIF1α availability, thereby restraining adipose tissue expansion during obesity and alleviating associated metabolic dysregulation." (PMID 41340654, 2025). "This dichotomy suggests dual targeting (inhibiting HIF-1α/activating HIF-2α) could synergistically ameliorate obesity-associated IR." (PMID 41039626, 2025). "Furthermore, a study revealed an association between PPARγ2 and HIF1α, since HIF1α attenuates adipogenesis and promotes white adipose tissue fibrosis in obesity by driving PPARγ S112 phosphorylation via autocrine/paracrine signaling." (PMID 36091035, 2022). "During the development of obesity, rapid adipose tissue expansion and adipocyte enlargement cause adipose tissue hypoxia and lead to an activation of hypoxia-inducible factor 1-alpha (HIF1-α), which induces the production of ECM proteins." (PMID 36119080, 2022). "Obesity triggers hypoxia in adipose tissue and the small intestine, which stabilizes and activates hypoxia-inducible factor-1α (HIF-1α), a transcription factor implicated in hypoxia and hepatic lipid accumulation, resulting in adverse metabolic effects, including insulin resistance and NAFLD." (PMID 34360607, 2021). "Apart from the general issues just mentioned, the involvement of HIF-1α, particularly in the progression of obesity and type 2 diabetes-associated NAFLD, has been traditionally related to its role (and then of HIF1) in regulating the expression of the genes involved in glucose and lipid metabolism." (PMID 34359934, 2021). "Moreover, in obese mice fed an HFD, increased HIF-1α and VEGF levels have been found, and HIF-1α overexpression was causally implicated in obesity-induced insulin resistance." (PMID 32984393, 2020). "One important factor that stimulates angiogenesis is hypoxia that results from tumor growth or due to other situations such as increase in adipose tissue caused by obesity, leading to the activation of hypoxia inducible factor-1α (HIF-1α) which in turn stimulates VEGF." (PMID 32984393, 2020). "Specifically, in the hypothalamic, HIF-1α is an important nutrient sensor and regulator of energy metabolism; it is also implicated in the regulation of hypothalamic neuroinflammation during the development of obesity." (PMID 30443205, 2018). "We hypothesized that BBR may alleviate obesity-induced adipose tissue fibrosis and associated metabolic dysfunction through inhibition of HIF-1α." (PMID 30622603, 2018).